RAB9B (RAB9B, member RAS oncogene family)
Description:
The small GTPases Rab are key regulators of intracellular membrane trafficking, from the formation of transport vesicles to their fusion with membranes. Rabs cycle between an inactive GDP-bound form and an active GTP-bound form that is able to recruit to membranes different sets of downstream effectors directly responsible for vesicle formation, movement, tethering and fusion (By similarity). RAB9B is involved in the transport of proteins between the endosomes and the trans Golgi network (By similarity). May use NDE1/NDEL1 as an effector to interact with the dynein motor complex in order to control retrograde trafficking of RAB9-associated late endosomes to the TGN.
Synonyms: Rab-9L; RAB9L
Tractability: Small molecule: a structure with a bound ligand is known. Antibody: UniProt places it where antibodies can reach, with high confidence; its Gene Ontology location is reachable by antibodies, with high confidence. PROTAC: ubiquitination databases record sites on it; its protein half-life has been measured.
Gene: Protein-coding gene on chromosome X (103,822,327 to 103,835,153, reverse strand). Ensembl gene ENSG00000123570.
Subcellular location: Cell membrane; Cytoplasmic vesicle, phagosome; Cytoplasmic vesicle, phagosome membrane
Pathways (Reactome):
Vesicle-mediated transport: RAB GEFs exchange GTP for GDP on RABs; Retrograde transport at the Trans-Golgi-Network
Immune System: Neutrophil degranulation
Metabolism of proteins: RAB geranylgeranylation
Signal Transduction: RHOBTB3 ATPase cycle
Gene Ontology:
Molecular function: G protein activity; GDP binding; protein binding; GTPase activity; GTP binding; identical protein binding
Biological process: receptor-mediated endocytosis; retrograde transport, endosome to Golgi; Rab protein signal transduction
Cellular component: phagocytic vesicle; cytosol; late endosome; lysosome; plasma membrane; secretory granule membrane; phagocytic vesicle membrane
Homologues: Orthologues: chimpanzee RAB9B (100% identical), pig RAB9B (99% identical), rat Rab9b (99% identical), mouse Rab9b (98% identical), tropical clawed frog rab9b (85% identical), dog RAB9B (82% identical), macaque RAB9B (82% identical), zebrafish rab9b (78% identical). Paralogues in human: RAB9A (76% identical), RAB7A (52% identical), RAB7B (40% identical), RAB26 (37% identical), RAB27A (37% identical), RAB11A (37% identical), RAB11B (37% identical), RAB13 (36% identical), RAB25 (36% identical), RAB37 (36% identical), RAB4A (36% identical), RAB4B (36% identical), and 56 more.
Diseases named in the same sentence as RAB9B in open-access papers:
RAB9B is named in the same sentence as 5 diseases in open-access papers, as found by Europe PMC text mining. Sharing a sentence is not in itself a finding about the gene and the disease. The quoted sentences say what the papers report.
colorectal cancer (1 paper, 2025). A primary or metastatic malignant neoplasm that affects the colon or rectum. "While there is no study on RGMB in AML, Jiang et.al found that RAB9B is overexpressed in colorectal cancer and promotes tumor growth and metastasis." (PMID 40608798, 2025).
lung carcinoma (1 paper, 2021). "Moreover, MS4A1 is dysregulated in asbestos-related lung squamous carcinoma, RAB9B is a target of miR-15/16 which are highly related to lung cancer, LINC00539 is related to tumor immune response while long non-coding RNA, OGFRP1, regulates non-small-cell lung cancer progression." (PMID 33672117, 2021).
tumor (3 papers, 2021 to 2025). "Our study establishes a Tumor Microenvironment-derived Prognostic Model (MPM) that integrates eight TME-associated genes (CXCL12, GZMB, ITPR2, LYN, RAB9B, RGMB, RUFY4, TRIM16) to stratify AML patients into distinct risk categories with significant survival differences." (PMID 40608798, 2025).
RAB9B also shares sentences with these, for which no sentence is quoted: infection (1 paper); non-small cell lung carcinoma (1).